SPANXD (SPANX family member D)
Synonyms: CT11.4; SPANX-D; SPANXE; SPANX-E; dJ171K16.1
Tractability: No criterion of Open Targets' tractability assessment is met for any kind of drug.
Gene: Protein-coding gene on chromosome X (141,697,411 to 141,698,739, reverse strand). Ensembl gene ENSG00000196406.
Subcellular location: Cytoplasm; Nucleus
Subcellular location (Human Protein Atlas): Nucleoplasm; Vesicles
Gene Ontology:
Molecular function: protein binding
Cellular component: nucleus; cytoplasm
Homologues: Paralogues in human: SPANXC (98% identical), SPANXA1 (94% identical), SPANXA2 (94% identical), SPANXB1 (78% identical).
Diseases named in the same sentence as SPANXD in open-access papers:
SPANXD is named in the same sentence as 1 disease in open-access papers, as found by Europe PMC text mining. Sharing a sentence is not in itself a finding about the gene and the disease. The quoted sentences say what the papers report.
cancer (1 paper, 2023). A tumor composed of atypical neoplastic, often pleomorphic cells that invade other tissues. "These included SPANXD and other SPANX (sperm protein associated with the nucleus on the X chromosome) family members, whose expression is restricted to spermatozoa and cancer cells." (PMID 37192000, 2023).